MALAT1 (metastasis associated lung adenocarcinoma transcript 1)
Diseases named in the same sentence as MALAT1 in open-access papers (continued):
Sharing a sentence is not in itself a finding about the gene and the disease.
tumor (continued). "In vivo injection of circ‐MALAT1 overexpressed cells (circ‐MALAT1 O/E) led to a larger tumor size, a higher tumor weight and a faster tumor growth rate than that of control cells (Vector and circ‐SPARC O/E)." (PMID 32099751, 2020). "MALAT1 has been found overexpressed in several human neoplasms and promotes tumor cell invasion and metastasis." (PMID 32916806, 2020). "Based on our results of clinical specimens and Oncomine and TCGA database, MALAT1 showed a higher level in tumor tissues and was connected with metastasis of CRC patients." (PMID 32209115, 2020). "On the contrary, CASC9, ENS-653, MALAT1 and UNC5B-AS1 associated positively with the advanced clinicopathological characteristics including large tumor size, advanced stage, or lymph node metastasis in PTC patients." (PMID 33158279, 2020). "LncRNAs can be categorized as oncogenic or tumor suppressor lncRNAs according to their biological functions during carcinogenesis, such as the well-known MALAT1, ANRIL and H19." (PMID 31907020, 2020). "More importantly, we evaluated the growth of xenograft tumor from the stably circ‐MALAT1‐overexpressed Huh7 cells." (PMID 32099751, 2020). "Consistent with previous studies, we confirmed that MALAT1 and miR-146a serve as transforming genes and tumor inhibitors in HCC neoplasia and progression, respectively." (PMID 32435156, 2020). "In CRC, MALAT1 can contribute to the tumor development via releasing oncogene polypyrimidine tract binding protein." (PMID 33005106, 2020). "It was suggested that high expression of MALAT1 was significantly correlative to LSCC patients who were characterized by large tumor size (>2 cm), advanced TNM grade (III‐IV), and metastatic lymph nodes (P < .05)." (PMID 31837057, 2020). "Recently, MALAT1 ASOs have been reported to reduce tumor growth in a preclinical mouse model for BC." (PMID 32575858, 2020). "Meanwhile, the loss‐of‐function experiments confirmed the anti‐proliferation, anti‐metastasis, and pro‐apoptosis roles of MALAT1 knockdown in NSCLC, and xenograft mouse model further verified the tumor‐promoter role of MALAT1 in vivo." (PMID 33146951, 2020). "Of note, MALAT1-silencing strategies led to inhibition of MM tumor growth, thus providing the preclinical rational for considering MALAT-1 a novel therapeutic target in MM." (PMID 33076518, 2020). "It is noteworthy that targeting MALAT1 globally inhibits the proliferation capacity of TSCCA-induced xenograft tumor, suggesting MALAT1 as an important prognostic factor of OSCC and a satisfactory target with therapeutic potential." (PMID 33123473, 2020). "In accordance with the cell results, MALAT1 showed a higher level in tumor tissues and was also identified to connect with metastasis of CRC patients." (PMID 32209115, 2020). "After injection for 27 days, the tumor volume and weight were declined by MALAT1 down regulation in Ox-treated mice in comparison with the control." (PMID 33005106, 2020). "While being a potential new biomarker for tumor stage diagnosis, further studies should be conducted on larger cohorts to confirm the predictive power of exo-MALAT1." (PMID 32438606, 2020). "At present, it is believed that MALAT1 is mainly responsible for regulating the proliferation, migration and invasion of tumour cells." (PMID 32993558, 2020). "Data suggested that the tumor volume and weight of xenografts in sh‐MALAT1 group were dramatically smaller than that in sh‐NC groups." (PMID 33146951, 2020). "MALAT1 has been defined as a promising anticancer target, because it is over-expressed and its knock-down produces strong anti-tumor effects in almost all tumor types." (PMID 32019064, 2020). "In the tumor tissues of IP groups, only the expression of MALAT1 showed a significant reduction in the high-dose Vc group." (PMID 33293956, 2020). "In detail, direct interaction between MALAT1 and miR-101-3p, which was demonstrated to be a tumor suppressor, impairs targeting and leads to VEGF-C overexpression." (PMID 32756406, 2020).
tumor (continued). "For example, some lncRNAs, such as NOC2L-4.1, TUG1, and MALAT1, are well established to promote tumour growth, while other lncRNAs, such as ASMTL-AS1, LINC02381, and LINC02499 have been found to inhibit tumour progression." (PMID 33243205, 2020). "We show that overexpression of FOXO1 in tumor tissues from xenograft mouse decreased MALAT1 expression significantly." (PMID 32708561, 2020). "A recent preclinical in vivo study identified MALAT1 as a potential tumor suppressor, preventing the formation of metastases in breast cancer." (PMID 33235218, 2020). "MALAT1 has critical roles in nuclear organization, epigenetic regulation, cell migration, and tumor progression." (PMID 31956395, 2020). "Further mechanism studies showed that MALAT1 can inhibit tumor cell apoptosis and induce cell migration and invasion by regulating the Wnt/beta-catenin signaling pathway, and overexpression of MALAT1 can induce epithelial mesenchymal transition (EMT)." (PMID 32185124, 2020). "For instance, a series of in vivo and in vitro experiments showed that MALAT1 knockdown can activate the Hippo cascade by upregulating miR‐181a‐5p, thereby hamper the proliferation and adhesion capacity of tumour cells in myeloma." (PMID 32779318, 2020). "Expression of MALAT1 confirmed that it played a diverse role in tumor prevalence and carcinogenesis of PTC in vivo." (PMID 32102500, 2020). "Increasing reports have indicated that MALAT1 can play parts in different tumors through working as a carcinogenic factor or anticancer factor due to the variation of tumor microenvironment." (PMID 33146951, 2020). "Whole transcriptome analysis was performed in three primary-tumor-derived OSCs obtained from fresh PCa explants before/after MALAT1 targeting." (PMID 33375130, 2020). "In this study, the relative mRNA expression of MALAT1 and miR‐145 was measured in tumour/serum samples genotyped as AA, AG and GG." (PMID 32720739, 2020). "Serum MALAT1 levels and tumor grade were independent prognostic factors for OS of patients receiving TMZ." (PMID 33634032, 2020). "Through the measurement and record, we found that tumor volume and weight declined in sh-MALAT1 group contrasted to sh-NC group." (PMID 31953613, 2020). "We note that one tumor (pRCC2-1410), which had the morphological features of pRCC2, showed the classic MALAT1-TFEB gene fusion." (PMID 32555180, 2020). "It has also been shown that MALAT-1 expression is associated with tumor-node-metastasis (TNM) stage and tumor differentiation; however, these findings remain a subject of debate." (PMID 33052949, 2020). "MALAT1 has been described as upregulated in NSCLC tumor tissues and cell lines, and it regulates cell proliferation, migration, invasion, EMT and apoptosis, but also mesenchymal-epithelial transition (MET)." (PMID 32438606, 2020). "The observed positive correlation between MALAT1 and Slug not only enriches our understanding of their functions in tumor development but also provides a more complete understanding of the MALAT1 lncRNA." (PMID 31466138, 2019). "The long noncoding RNA MALAT1 was selected due to its ubiquitous expression in both normal and tumor cells." (PMID 31303442, 2019). "In the established xenograft model, MALAT1 promoted tumor growth by regulating the expression of miR-142-3p." (PMID 31168355, 2019). "In our previous reports, we have shown in 124 CRC tumor specimens that MALAT1 had higher expression levels in recurrent primary and metastatic sites, relative to non-recurrent primary tumors." (PMID 31665047, 2019). "Studies have confirmed that MALAT1 inhibits miR-101 expression, and miR-101 regulates apoptosis, cellular stress, metastasis, autophagy, and tumor growth." (PMID 31249598, 2019). "MALAT1 was shown to influence tumor progression and prognosis in ccRCC, as well as acting as a competing endogenous RNA by sponging the miRNA-200 family." (PMID 31627266, 2019).
tumor (continued). "LncRNAs have been reported to involve in the regulation of tumor metastasis such as MALAT-1 and HOX antisense intergenic RNA (HOTAIR)." (PMID 31085800, 2019). "Subsequent mouse brain MRI and H&E staining revealed that tumor volume in the MALAT1-KD group was much smaller than the mis-shRNA group and the NC group (p < 0.05)." (PMID 31648104, 2019). "The average profile of MALAT1 in tumor cells was over 4-fold higher than in the corresponding normal cells." (PMID 31788131, 2019). "Experiments both in vitro and in vivo have revealed that MALAT1 is a proliferation promoter, as well as accelerating tumor development and metastasis in triple-negative breast cancer (TNBC)." (PMID 31214490, 2019). "Tumor suppressive lncRNAs (GAS5, MEG3, FER1L4 and LINC00672) and oncogenic lncRNAs (CCAT2, BANCR, NEAT1, MALAT1, H19 and Linc-RoR) have been identified as key regulators of the established tumor suppressor or oncogenic pathways in EC." (PMID 30781521, 2019). "Previous in vitro and xenograft studies demonstrated that MALAT1 promotes cell proliferation, migration, tumor growth, metastasis, and chemoresistance." (PMID 30781877, 2019). "Then, in this model, the application of ASOs against MALAT1 resulted in slower tumor proliferation and a reduction in metastasis." (PMID 31448238, 2019). "ASO has been used to downregulate MALAT1 lncRNA expression in mouse mammary tumor virus-PyMT mice and organoids, resulting in decreases in tumor cell proliferation and metastasis." (PMID 31340867, 2019). "Upregulated expression of MALAT1 is observed in a plethora of tumours including breast, lung, colorectal or cervical cancers." (PMID 31382922, 2019). "Then, the cell lines were used to establish a xenograft model to investigate the role of MALAT1 in tumor growth." (PMID 31168355, 2019). "In this study, for the first time, we found that both lncRNAs H19 and MALAT1 showed high expression level in tumor specimens of GIST patients." (PMID 31827510, 2019). "This investigation is consistent with the previous report that MALAT1 expression is up-regulated significantly in GSCs compared with tumor cells, and miR-129-5p is down-regulated in GSCs." (PMID 32117213, 2019). "As it promotes proliferation and/or dissemination of tumor cells, the level of MALAT1 correlates with tumor size, stage, and overall prognosis." (PMID 30682861, 2019). "High expression levels of MALAT1 in paraffin tumor tissue have been detected in 8 out of 16 (50%) GIST patients harboring c-KIT mutations as compared to 1 out of 4 (25%) wild-type patients." (PMID 31827510, 2019). "Studies have confirmed that MALAT1 is upregulated in various tumor tissues, such as NSCLC, breast cancer, cervical cancer, and bladder cancer, and is closely associated with the occurrence, development, and metastasis of tumors." (PMID 31757221, 2019). "It was confirmed that the expression of MALAT1 was upregulated in various types of tumors and that MALAT1 has a significant influence on tumor cell proliferation, migration, invasion, and apoptosis." (PMID 31168355, 2019). "The knockdown of MALAT1 significantly inhibited tumor growth, while the ectopic expression of MALAT1 significantly promoted tumor growth." (PMID 31168355, 2019). "Functionally, MALAT1 is considered as an oncogenic lncRNA because of its role in promoting tumor differentiation, proliferation, migration, invasion, EMT, and chemoresistance." (PMID 31480503, 2019). "Overexpression of MALAT1 has been observed in a large number of tumor types including breast, pancreas, colon, prostate, and liver." (PMID 32099603, 2019). "On the other hand, none of clinicopathological variables showed any correlation with MALAT1 methylation status in the tumor tissue." (PMID 32099603, 2019). "Elevated MALAT1 expression has been reported to be positively correlated to lymphatic metastasis and tumor size but negatively correlated with the overall survival of GBC patients." (PMID 31174563, 2019).
tumor (continued). "In contrast, other studies reported that MALAT1 inhibits cell proliferation, tumor growth, invasion, and epithelial-mesenchymal transition (EMT)." (PMID 30781877, 2019). "Metastasis-associated lung adenocarcinoma transcript 1 (MALAT1) is a highly conserved lncRNA, and its over-expression in multiple cancerous tissues has been linked to the proliferation and metastasis of tumor cells." (PMID 31795964, 2019). "In this section, we discuss several molecular mechanisms by which MALAT1 regulates tumor progression and metastasis." (PMID 30781877, 2019). "In a previous research, the MALAT1 expression was explored in tumor tissues and adjacent normal thyroid tissues in FTC patients." (PMID 31788131, 2019). "Numerous studies on this gene have shown that MALAT1 plays a vital role in tumor progression and can be used as a tumor prognostic marker." (PMID 32099603, 2019). "Of the 17 annotated SNPs in MALAT1, SNP rs3200401 (C6600U) resides in H160, which contains a binding site for the tumor suppressor miR-217-5p." (PMID 31717552, 2019). "MALAT1 is a nuclear localized lncRNA and targeted inhibition of MALAT1 expression by ASOs significantly reduces tumor growth and metastasis." (PMID 29732012, 2018). "Our results demonstrated that MALAT1 promotes proliferation and invasion abilities of both malignant tumor cells through different molecular mechanisms." (PMID 29416769, 2018). "MALAT1 silencing by siRNAs antagonized tumor cell proliferation and migration, and triggered apoptosis, both in vitro and in xenograft murine models in vivo." (PMID 29739426, 2018). "Tumor epithelial cells overexpressing MALAT1 showed marked diffuse nuclear signals with numerous nuclear speckles." (PMID 29739426, 2018). "Multiple lines of evidence have reported aberrant expression and prognostic usefulness of tissue MALAT1 across several tumor types, along with diverse and context-dependent molecular mechanisms leading to the acquisition of the malignant phenotypes." (PMID 29739426, 2018). "It has been reported that Malat1 drives tumorigenesis through the promotion of tumor cell proliferation." (PMID 29891768, 2018). "A preclinical study demonstrated that the use of modified ASOs targeting MALAT1 in a breast cancer mouse model promotes cystic differentiation and decreases tumor growth." (PMID 29458374, 2018). "Meanwhile, the expression of MALAT1 and miR‐140‐5p in the formatted tumor nodes were measured by qRT‐PCR." (PMID 30094957, 2018). "Expressions of linc-ROR and MALAT1 in TT varied significantly with different tumour grade (Kruskal-Wallis: p = 0.0348 and p = 0.0454)." (PMID 30205577, 2018). "MALAT1 was frequently overexpressed and performed as an oncogene in several human tumor entities, including lung, breast, pancreas, colon, and liver." (PMID 30591689, 2018). "Linc-ROR was most expressed in G3 tumours and MALAT1 expression, which was downregulated in tumour tissue, declined with tumour grade and reached the minimum in G3 tumours." (PMID 30205577, 2018). "It was later demonstrated to be a necessary factor in a mouse xenograft model of NSCLC metastasis, which was proved by employing antisense oligonucleotides (ASOs) to deplete MALAT1 in the xenograft tumours studied." (PMID 29685978, 2018). "Transfection of two different LNA-gapmeRs targeting MALAT1 (henceforth referred to as g#5 and g#9) significantly reduced MALAT1 expression, and this effect translated into reduced viability and migration of tumor cells." (PMID 29487387, 2018). "The metastasis-associated lung adenocarcinoma transcript 1 gene (MALAT1, NEAT2) is the first discovered human tumor-related lncRNA that promotes the progression and metastasis of cancers." (PMID 30154407, 2018). "Knockdown MALAT1 expression level in PCa cell lines inhibited cellular proliferation, invasion, and tumor formation." (PMID 30591689, 2018).
tumor (continued). "In vitro studies revealed that knock-down of MALAT1 reduced cell proliferation, migration and number of tumor spheres representing putative stem cell-like cells, along with increasing cell apoptosis." (PMID 29739426, 2018). "The tumor-promoting role of MALAT1 has been demonstrated in a variety of solid malignancies, where it modulates essential pathways promoting proliferation, escape from apoptosis, migration and invasion." (PMID 29487387, 2018). "Mechanistically, MALAT1 association with PRC2-component Suz12 led to reduction of E-cadherin and induction of N-cadherin, triggering EMT in vitro and tumor growth and dissemination in vivo." (PMID 29739426, 2018). "Many miRNAs, including miR-205, miR-200c, and miR-204, have been reported to interact with MALAT1 and thus contribute to its tumor-promoting mechanism in various cancer types." (PMID 28793797, 2018). "Schmidt then demonstrated that siRNA-mediated knockdown of MALAT1 significantly impaired migration and invasion in vitro, as well as in vivo tumor growth in mice." (PMID 29739426, 2018). "We subcutaneously injected si-MALAT1 or si-NC transfected A549 and H1299 cells that stably expressed luciferase into nude mice and assessed xenograft tumor growth by bioluminescence imaging." (PMID 29484127, 2018). "One limitation of our cohort is the limited group of progressed patients with metastases or large tumours, as the stated MALAT1 studies were mainly composed of T4 stage patients with lymph node involvement." (PMID 30205577, 2018). "In summary, we have identified a novel regulatory axis that IL-8/STAT3/MALAT1 in the effort of elucidating the tumor-promoting the function of M2 macrophages." (PMID 30591689, 2018). "Recently, emerging evidence has demonstrated that aberrantly expressed MALAT1 involves in the tumorigenesis and tumor progression in HNC." (PMID 29416703, 2018). "This study also firstly analyzed the association of MALAT1 with tumour differentiation, distant metastasis, TNM stage and tumour size." (PMID 30093838, 2018). "Down-regulated NKILA or highly expressed MALAT1 and UCA1 are associated with tumor metastasis, especially lymph node metastasis." (PMID 29416703, 2018). "Recently, increasing evidence provided that MALAT1 play a pivotal role in promoting proliferation, migration, metastasis and invasion of tumor cell." (PMID 30093838, 2018). "In vivo xenograft animal model, delivery of siRNA against MALAT1 contributed to the delay of tumor growth and inhibition of metastasis." (PMID 30037351, 2018). "In vivo studies showed that siRNA-mediated depletion of MALAT1 reduced tumor formation in mice and enhanced animal survival, supporting is potential as therapeutic target." (PMID 29739426, 2018). "In contrast, loss of WIF1 enhanced the activity of the metastasis-associated lung adenocarcinoma transcript 1 (MALAT1), a long non-coding RNA and a key positive regulator of tumor invasion." (PMID 29462960, 2018). "In lung cancer cell lines, serum exosome-derived lncRNA MALAT-1 promotes tumor migration and prevents tumor cells from apoptosing." (PMID 29678180, 2018). "It has been demonstrated by in vivo and in vitro studies that MALAT1 promotes proliferation, tumor development and metastasis of TNBC." (PMID 29416769, 2018). "Mutations in lncRNAs like HOTAIR, MALAT1, ANRIL, h19 and PCA3 have been reported in a number of tumor types." (PMID 29732012, 2018). "First, we observed that M2 macrophages increased overexpression level of MALAT1, and promoted tumor progression in PCa." (PMID 30591689, 2018). "An association with T stage was detected for MALAT1/ANRIL (Kruskal-Wallis: p = 0.006) with a decreasing trend with rising tumour stage (Spearman: p = 0.0003)." (PMID 30205577, 2018). "Patients with high expression level of MALAT1, associated with elevated levels of α-fetoprotein (AFP), have a significantly increased risk of tumor recurrence after liver transplantation." (PMID 29495592, 2018).